TLR4 (toll like receptor 4)
Diseases named in the same sentence as TLR4 in open-access papers (continued):
Sharing a sentence is not in itself a finding about the gene and the disease.
Sepsis (continued). "In conclusion, the results of this meta-analysis showed that toll like receptor 4 gene rs4986790 and rs4986791 polymorphisms might not have independent association with sepsis susceptibility." (PMID 27958344, 2016). "The results of this meta-analysis suggest that the rs4986790 and rs4986791 polymorphisms in toll like receptor 4 gene may have no statistically significant influence on sepsis susceptibility." (PMID 27958344, 2016). "However, it is yet early to exclude targeting the TLR4 pathway for sepsis." (PMID 25766838, 2015). "Genotyping analysis of eight SNPs in TLR4 and CD14 genes were performed by using Snapshot SNP genotyping assays and DNA sequencing methods to investigate whether the gene polymorphisms are associated with susceptibility to sepsis." (PMID 25394369, 2014). "Additionally, during a trauma situation or severe sepsis, platelets may respond to LPS through TLR4 to activate neutrophil extracellular traps to ensnare bacteria." (PMID 24489676, 2014). "However, the renal effects of TLR4 antagonism are incompletely investigated, and there are reasons to believe that TLR4 may be an important mediator of sepsis-induced AKI." (PMID 25182709, 2014). "Thus, it is possible that some patients with sepsis would still benefit from TLR4 inhibition." (PMID 25182709, 2014). "TLR2 and TLR4 are potent initiators of the inflammatory and immune response, triggering intracellular signaling cascades that eventually result in the increase of the expression of pro-inflammatory cytokines, therefore playing an important role in sepsis pathogenesis." (PMID 23552565, 2013). "Although the exact role for TLRs in CM remains to be elucidated, a number of studies suggest that the pathogenesis of PbA-induced SM is independent of TLR4, unlike the pathogenesis of sepsis where mice deficient in TLR4 are highly resistant to the development of LPS-induced septic shock." (PMID 23506269, 2013). "Thus, TLR4 is regarded as a primary target for treating sepsis." (PMID 24302927, 2013). "Indeed, IR and overt type-2 diabetes may emerge during human infections and sepsis via activation of toll-like receptor 4 (TLR-4) signaling." (PMID 22709547, 2012). "In the present study, we used the CLP model to determine whether CERA protects against tissue damage in sepsis-induced multi-organ dysfunction, as well as to test the hypothesis that local renal TLR4 and pro-inflammatory pathways mediate sepsis-induced multi-organ dysfunction and AKI." (PMID 22235348, 2012). "Thus, our data indicate that SRA is required for a maximal TLR4/NFκB response to CLP sepsis." (PMID 23071440, 2012). "Importantly, the contribution of TLR4 signaling in the two models of sepsis may differ significantly." (PMID 21977329, 2011). "Indeed, while the expression of TLR4 on cardiac myocytes is known for years, the use of eritoran recently helped identify, in animal models, the role of TLR4 and intra-cellular signalling as one of the mechanism involved in sepsis-related cardiac dysfunction." (PMID 20396414, 2010). "The frequencies of both genetic variations in TLR4 and TIRAP/Mal have been recently studied worldwide in a comparative fashion, and it has been proposed that differences between regional populations can be attributed to selective pressure due to differences in sepsis susceptibility." (PMID 20525286, 2010). "Interestingly we could show in our study a relatively lower receptor expression (CD14, TLR2 and as a trend in TLR4), in patients with sepsis that died, compared to patients that survived." (PMID 19371402, 2009). "Inflammatory mediators were markedly increased in sepsis (TNF-α, IL-6, HMGB1, TLR-4, and NF-κB; all p < 0.001 vs. Control) and significantly downregulated by pioglitazone (p < 0.01, p < 0.001, p < 0.001, p < 0.01, p < 0.01 vs. CLP + Saline, respectively)." (PMID 41899201, 2026). "Fortunellin ameliorates inflammation and oxidative stress in sepsis-induced AKI, possibly through the modulation of the TLR4/NF-κB pathway." (PMID 40989844, 2025).
Sepsis (continued). "Recognition of bacterial PAMPs by TLRs (TLR2, TLR4, TLR5, TLR9) activates NF-κB via MyD88-dependent and -independent pathways, leading to pro-inflammatory cytokine production and potentially sepsis." (PMID 40386784, 2025). "For example, in sepsis, a positive feedback loop is formed between the HMGB1—TLR4 axis and the NLRP3 inflammasome, which amplifies the pro—inflammatory response." (PMID 40877572, 2025). "Studies have shown that prolonged or excessive activation of TLR4/MD2 can result in various inflammation-related conditions, such as sepsis, atherosclerosis, and autoimmune diseases." (PMID 39976020, 2025). "In animal experiments using mouse models of sepsis, researchers applied the inhibitor TAK-242 to block TLR4 activation." (PMID 41041277, 2025). "Extracellular HMGB1 binds to TLR4 and receptors for advanced glycation end-products (RAGE) to exacerbate inflammation in sepsis." (PMID 40421030, 2025). "The multifunctional antibacterial drugs that can inhibit both TLR4 and TLR2 signaling pathways to control excessive inflammation are anticipated to be promising therapeutics to treat sepsis." (PMID 40963927, 2025). "The in vivo efficacy of KT-474 has also been evaluated in mouse models of TLR4-induced ALI and sepsis, where it exhibited significant anti-inflammatory activity." (PMID 40771916, 2025). "In this study, we first performed the bioinformatic analysis on the pediatric and adult septic patient datasets to demonstrate the clinical significance of TLR4 and TLR2 inhibition as a promising therapeutic approach in treating sepsis." (PMID 40963927, 2025). "Simultaneous blockade of the HMGB1—TLR4 axis (e.g., via neutralizing antibodies) and the NLRP3 inflammasome (e.g., using MCC950) can decrease the secretion of IL—1β in experimental sepsis models." (PMID 40877572, 2025). "It has previously been demonstrated that TLRs such as TLR-2, TLR-3, TLR-4, and TLR-7 are highly expressed in the lung tissues of septic mice, therefore suggesting a potential role in the pathogenesis of ARDS during sepsis." (PMID 40076895, 2025). "The gene differential expression analysis showed that compared with the healthy group, the sepsis patient group exhibited significantly lower expression levels of AKT1 and BCL2, but significantly higher expression levels of MMP9, ICAM1, TLR4, and HIF1A." (PMID 41411324, 2025). "NINJ1 facilitates immune cell migration to sites of inflammation and promotes inflammation through Toll-like receptor 4 (TLR4) signaling activation, as demonstrated in a sepsis mouse model." (PMID 40075648, 2025). "Its interactions with TLR2, TLR4, and RAGE drive inflammation, contributing to the cytokine storm in sepsis and promoting multiorgan damage." (PMID 40779122, 2025). "During sepsis, the S100A8/A9 complex activates the classical Toll-like receptor 4 (TLR4) signaling pathway in monocytes, inducing the expression of pro-inflammatory mediators related to NF-κB, and can be released as a DAMP." (PMID 40568710, 2025). "Numerous studies have demonstrated the critical role of the TLR4/MAPK pathway in LPS-induced production of inflammatory mediators, which are key elements in the progression of sepsis." (PMID 40524158, 2025). "In a sepsis-induced AKI model, USP9x inhibits the ubiquitinated degradation of toll-like receptor 4 (TLR4), which is involved in inflammatory responses and apoptosis by activating the NF-κB signaling pathway through interaction with lipopolysaccharide (LPS)." (PMID 40225869, 2025). "Among these inhibitors, the TLR4 inhibitor TAK—242 exhibits promise in the treatment of inflammatory diseases, including sepsis and acute lung injury, by obstructing the LPS—or HMGB1—mediated signaling pathways." (PMID 40877572, 2025). "Future research should focus on exploring targeted intervention strategies for key pathways including TLR4, PD-L1, and FABP4, aiming to protect the structural and functional integrity of LSECs and improve sepsis-related immune imbalance and organ dysfunction." (PMID 40072101, 2025).
Sepsis (continued). "However, increased production of TNF-α is not parallel with TLR2 and TLR4 expression levels on leukocytes, which may cause increased susceptibility to sepsis in the elderly." (PMID 40379629, 2025). "It was reported that NF-κB is activated with TLR-4 and promotes the level of TNF-α, IL-16, and IL-6 in the tissue of sepsis rats." (PMID 41221897, 2025). "ADAP regulates sepsis progression by controlling the TLR4-induced upregulation of PDPN to form a PDPNhi macrophage subpopulation, which exerts enhanced antibacterial functions during sepsis." (PMID 39903516, 2025). "Moreover, studies have shown that TLR4 knockout mice were resistant to Gram-negative bacteria-induced septic shock 11 whereas TLR2-deficient mice had increased survival rates compared with the wild-type ones in a polymicrobial sepsis model." (PMID 40963927, 2025). "eCIRP stimulates neutrophil DLL4 expression via TLR4, leading to the elevated DLL4+ neutrophil phenotype in the blood and lungs in sepsis." (PMID 41392977, 2025). "Further investigations have also explored the role of PLGA nanoparticles in improving the delivery of TLR4 and TLR9 ligands for treating sepsis and sepsis‐related organ injuries." (PMID 40599085, 2025). "In our study, 6 key target genes involved in sepsis and COVID-19 treatment with JHD were identified including AKT1, MMP9, ICAM1, TLR4, BCL2 and HIF1A based on PPI network." (PMID 41411324, 2025). "Specifically, upon GAS5 knockdown, TLR4 overexpression mitigates the reduction in inflammatory cytokines and subsequent cell death, an indication that GAS5 enhances sepsis-related inflammatory responses through altering the miR-23a-3p/TLR4 axis." (PMID 39941145, 2025). "Two TLR4 antagonists—eritoran and resatorvid (TAK-242)—were enrolled in clinical trials focused on sepsis and septic shock treatment." (PMID 41010682, 2025). "The identification of the tubular TLR2/NF-κB/CCL2 signaling pathway and the inhibition of the TLR4/NF-κB pathway represent promising strategies for addressing purulent AKI and related renal injuries in sepsis." (PMID 40386784, 2025). "Compared to both the vehicle and sepsis groups, a single dose of ghrelin administered immediately after the CLP procedure significantly lowered serum TLR4 levels (P <0.001)." (PMID 39144689, 2024). "In summary, TLR4-TIR acetylation promoted M1 macrophages polarization induced by LPS and pro-inflammatory cytokines secretion in the mouse model of sepsis." (PMID 39294473, 2024). "Irisin treatment suppressed inflammation, apoptosis, and pyroptosis by blocking the Toll-like receptor 4 (TLR4) and NLRP3 inflammasome signaling in vivo and in vitro and attenuated myocardial dysfunction in sepsis." (PMID 38540711, 2024). "In patients with sepsis, changes in the expression of TLR2 and TLR4 are more active on neutrophils than on monocytes." (PMID 39720715, 2024). "In animal sepsis models, multiple molecules such as TAK-242, eritoran, and TIRAP decoy peptides block TLR4 signaling at different stages through various modes of action, thereby enhancing the chances of survival for septic mice and lowering cytokine levels." (PMID 39606629, 2024). "Monocytes were obtained by sorting with TLR4-TIR-acK and CD16 antibodies from both normal individuals and sepsis patients." (PMID 39294473, 2024). "Numerous reports on sepsis highlight the importance of TLR2, TLR3, and TLR4 in cardiac dysfunction and cardiomyopathy, although their precise roles remain incompletely understood." (PMID 39201339, 2024). "To explore the influence of propofol on macrophage plasma membrane TLR4 in vivo, we performed standardized CLP on male mice, the most reliable model in sepsis research." (PMID 38549133, 2024). "The intersection of TLR4 and TRP signaling pathways, as well as the TRP-mediated effect on sepsis development and the immune response identified to date, represent a promising area of research." (PMID 38731999, 2024).
Sepsis (continued). "TLR4 synergistically recognizes and binds to LPS and has a similar effect, while TLR3 activation leads to improved survival in sepsis models." (PMID 38352879, 2024). "We observed significant acetylation of TLR4-TIR in monocytes, particularly in CD16+ monocytes, in patients with sepsis." (PMID 39294473, 2024). "Consistent with findings in sepsis and other cardiomyopathy models, TLR2 KO and TLR3 KO are shown to be protective, whereas TLR4 KO exacerbates cardiac dysfunction and cardiomyopathy." (PMID 39201339, 2024). "Second, Toll-like receptor-4 (TLR4) and CD14 antagonists are being explored as therapeutic drugs for sepsis." (PMID 39606629, 2024). "In the inflammatory landscape of sepsis, markers like P2X7R, TLR4, IL-1Β, and TNF-α take center stage." (PMID 38546748, 2024). "Conversely, the expression levels of pro-apoptotic and pro-inflammatory markers Caspase-3, P2X7R, TLR4, IL-1β, and TNF-α were found to be significantly escalated in the CLP group, which was indicative of the potent inflammatory response triggered by sepsis." (PMID 38546748, 2024). "TLR-4-dependent pathways can be activated by lipopolysaccharide (LPS) and endogenous substances generated during sepsis, as seen in the CLP, which increased the expression of TLR4." (PMID 37900081, 2023). "Previous research showed that in sepsis, CIRP adheres to the TLR4/MD2 complex on CD8 + and CD4 + T-cells, resulting in their activation and the production of TNFα and HMGB1 from APCs." (PMID 36920542, 2023). "These natural small-molecule compounds can modulate many signaling pathways, such as NF-κB, TLR4, MAPK, NLRP3, AMPK, and PI3KAKT, to prevent and treat sepsis." (PMID 37628912, 2023). "In a sepsis induced ARDS rat mode, after the use of anti-TLR4 monoclonal antibodies, down-regulating expression of TLR4, MyD88, and NF-κB in macrophages and its alleviated pulmonary inflammatory injury were observed." (PMID 38035100, 2023). "Key findings: MAF reduces LPS‐induced inflammatory reaction in vitro and in vivo; MAF exerts its anti‐inflammatory effect by inhibiting the TLR4/MyD88/NF‐κB pathway; MAF corrects intestinal flora imbalance during early stage of sepsis to some degree." (PMID 38455195, 2023). "The proinflammatory activity of HMGB1 in sepsis can be attributed directly to its binding to receptors such as the Receptor for Advanced Glycation End-products (RAGE) and Toll-like Receptor 4 (TLR4)." (PMID 36865384, 2023). "Accordingly, modulation of the TLR4/NF-κB signaling pathway has been a therapeutic target for sepsis, and several candidates, such as eritoran and TAK-242, which are inhibitors of TLR4, have shown partial efficacy in both animal studies and clinical trials." (PMID 36675101, 2023). "Pharmacological suppression of pCTS-L with neutralizing polyclonal and monoclonal antibodies attenuated pCTS-L–mediated inflammation by impairing its interaction with TLR4 and RAGE receptors, and consequently rescued animals from lethal sepsis." (PMID 36735789, 2023). "Moreover, during sepsis caused by Gram-negative bacteria, excessive TLR4/NF-κB activation may result in fatal septic shock." (PMID 37891903, 2023). "During sepsis, LPS is regarded as a main PAMP and activates TLR4 expressed on the surface of immune cells to stimulate pro-inflammatory cytokine production." (PMID 37754228, 2023). "The binding of LPS or TNF-α to their respective receptors triggers the activation of Toll-like receptor 4 (TLR4), MAPK and nuclear factor kappa B (NF-κB) signaling pathways, leading to the release of cytokines, which plays a crucial role in sepsis development." (PMID 37869005, 2023). "It is shown that the activation of TLR4/NF-κB and JAK2/STAT3 pathways induced apoptosis and inflammation during sepsis." (PMID 37650558, 2023).
Sepsis (continued). "Despite the moderate inhibition of the TLR4 activity of rhamnetin, as shown in the SEAP assay, rhamnetin showed substantial antiseptic activity in a mouse model of sepsis, which led us to investigate further mechanisms by which it prevented sepsis." (PMID 37958587, 2023). "By blocking the downstream signal transduction pathways of TLR-4 and NF-kB, Xanthohumol was shown to lessen cardiac damage in male mice during CLP-induced polymicrobial sepsis." (PMID 37900069, 2023). "Our study found that the expression of TLR4/NF-κB signaling was increased, and the expression of PI3K/Akt signaling was decreased, in rats with sepsis-induced ALI." (PMID 37175637, 2023). "In conclusion, this work explored the impact of PICK1 on the regulation of TLR4 and NF-κB expression, as well as the sepsis-induced ALI in CLP mice, providing a research direction for the prevention and treatment of the sepsis-induced ALI." (PMID 37488153, 2023). "However, excessive TLR4 activation disrupts immune homeostasis by sustaining pro-inflammatory cytokine and chemokine production, thus contributing to the onset and progression of various diseases, including Alzheimer’s disease, cancer, osteoarthritis, and sepsis." (PMID 38001481, 2023). "Survival analyses revealed that sepsis cases with low levels of mRNA of ADRB2, QDPR, SCAP, and TLR4 had worse overall survival." (PMID 38011291, 2023). "The impact of the PICK1 protein on the TLR4 signaling pathway was further investigated by detecting mouse macrophages, which revealed that PICK1 knockout sepsis-induced liver injury mice had the strongest NF-κB activity in sepsis-induced liver injury mice." (PMID 37488153, 2023). "The results of the study showed that PB2 helps to treat sepsis-induced ALI by controlling cytokine storms and reducing inflammation by altering the expressions of the TLR4/NF-κB, PI3K/Akt, Hippo and Rho signaling pathways." (PMID 37175637, 2023). "It had previously undergone clinical trials as a treatment for severe sepsis, while IAXO-102 is a synthetic glycolipid that modulates TLR4 activation and signalling by interfering selectively with the TLR4 co-receptors CD14 and MD-2." (PMID 35867263, 2023). "Induction of ER stress due to CIRP release in sepsis can be blocked by creating knockout of TLR4 or CIRP in mice, suggesting that CIRP can modulate ER stress through TLR4 signaling pathway." (PMID 36865547, 2023). "In the present work, we used IL-12/23p40 as a biomarker of enteric infection and sepsis and a marker of the possible effectivity of commensal pig bacteria (RP36, RP37, and LA) to modulate the TLR4/MD-2 signaling pathway." (PMID 38003758, 2023). "Our research demonstrated that in mice with sepsis-induced ALI, the lung tissue showed an increase in the expression of TLR4/NF-κB signaling and a decrease in the expression of PI3K/Akt signaling." (PMID 37175637, 2023). "A study has revealed that inhibition of the TLR4/NF‐κB pathway decreases liver injury in CLP‐induced sepsis rats, which suggests a participation of this pathway in sepsis‐induced liver injury." (PMID 38455195, 2023). "TAK-242 is a small molecule inhibitor of TLR4 that disrupts the interaction of the TIR domain with TIRAP and TRAM, and mitigates sepsis induced by endotoxins and polymicrobial peritonitis." (PMID 37215126, 2023). "It was observed earlier that administration of GM-CSF in sepsis patients reversed the monocytic deactivation by increasing HLADR and TLR4-induced cytokine production, as well as decreased the time of mechanical ventilation and length of hospital." (PMID 35720398, 2022). "The platelet toll-like receptor 4 (TLR4), belonging to the PRR family, is necessary for NETs formation for clearance of bacteria during sepsis." (PMID 35432313, 2022). "The EVs containing histones released by mouse-derived BMDM interact with TLR4, displaying pro-inflammatory effect, which can promote the production of TNF, IL-6 and IL-1β, thereby increasing the lethality of sepsis." (PMID 35463634, 2022).